MIR193BHG (MIR193b-365a host gene)
Synonyms: lincNORS; HypERlnc
Gene: Long non-coding RNA gene on chromosome 16 (14,301,069 to 14,331,067, forward strand). Ensembl gene ENSG00000262454.
Diseases named in the same sentence as MIR193BHG in open-access papers:
MIR193BHG is named in the same sentence as 1 disease in open-access papers, as found by Europe PMC text mining. Sharing a sentence is not in itself a finding about the gene and the disease. The quoted sentences say what the papers report.
tumor (1 paper, 2022). "LncRNA U62317.1, MIR193BHG, AC121338.2, and LINC02027 were highly expressed in tumor cells, while AC156455.1 showed the opposite trend." (PMID 35860590, 2022).